PKD2 (polycystin 2, transient receptor potential cation channel)
Diseases named in the same sentence as PKD2 in open-access papers (continued):
Sharing a sentence is not in itself a finding about the gene and the disease.
tumor (continued). "Vegfa expression/secretion by gastrointestinal tumor cells and Vegf-stimulated blood vessel formation is upregulated by PKD2." (PMID 29258556, 2017). "IHC staining for phospho-PKD2 (p-PKD2) was evaluated in 40 liver tumor tissues and 20 non-tumor liver tissues from clinical HCC patients." (PMID 26683365, 2016). "CRT0066101 treatment resulted in a suppression of p-PKD2 in both the primary tumor nodules and the metastasis tumor nodules." (PMID 26683365, 2016). "After 5 days, a pronounced sprouting of chicken-derived blood vessels into the tumour-like structures of PKD2-induced EBs was observed." (PMID 26148697, 2015). "Several reports suggest PKD2 to act as the predominant isoform promoting physiologic and tumour angiogenesis." (PMID 26148697, 2015). "PKD2 is also known to participate in tumor cell migration and invasion." (PMID 39408603, 2024). "High PKD2 protein expression was predominant both in oropharyngeal (31% vs. 2%) and laryngeal (27% vs. 4%) tumors, while low and high expressions were nearly equal in the hypopharyngeal tumor samples (20% vs. 16%, respectively)." (PMID 39408603, 2024). "Of the 55 tumor samples, 41 (75%) cases showed high PKD2 levels." (PMID 39408603, 2024). "We found that high PKD2 levels were detected more frequently in samples of elevated tumor grades and poorly differentiated tumor cells, which results may be consistent with the contribution of PKD2 to EMT of HNSCC." (PMID 39408603, 2024). "Whether this is also the case in TNBC cell lines and contributes to the PKD2/3-dependent tumor-promoting phenotype awaits investigation." (PMID 37293129, 2023). "Notably, the in vivo animal experiments also confirmed that circ-PKD2 inhibited tumor proliferation and activated autophagy in OSCC cells." (PMID 35220397, 2022). "Furthermore, lnc-PKD2-2-3, miR-328, and GPAM were also observed to be linked with advanced tumor features such as differentiation and tumor stage in CCA patients, which result from regulation of tumor stemness, growth, and metastasis." (PMID 35965521, 2022). "Compared to PKD1, PKD2 and PKD3 are often associated with tumor progression." (PMID 34249722, 2021). "In addition, lnc-PKD2–2-3 was positively correlated with CSC markers in CCA tumor tissues and was markedly upregulated in CCA stem-like cells compared with that in normal CCA cells." (PMID 33588867, 2021). "Interestingly, IFN-γ induces the expression of PD-L1 in tumor cells and also the protein kinase D isoform 2 (PKD2), an important regulator of PD-L1 in OSCC." (PMID 32630659, 2020). "In view of the similarity of the underlying biochemical abnormality in PKD2 and NF1, the presence of both conditions in a single individual might lead (under this hypothesis) to a more severe disease particularly in terms of tumor progression." (PMID 32533764, 2020). "In addition, circ-PKD2 weakened the tumor-promoting effects of miR-204-3p-driven APC2 on OSCC development through various signaling pathways." (PMID 32041942, 2020). "Notably, cleavage of HSP90 was followed by the degradation of PKD2, a crucial regulator of tumor growth and angiogenesis." (PMID 30858416, 2019). "Importantly, under in vivo condition or in the presence of an activating mitogen such as GRP or bombesin, PKD1 and PKD2 act to promote tumor cell proliferation." (PMID 30419840, 2018). "Moreover, compared with the tumor with no recurrence potential, the expression of p-PKD2 in recurrent tumor was significantly higher, and there was a moderate correlation between the positive rate of p-PKD2 and the recurrence status of the patients." (PMID 26683365, 2016). "However, PKD2 activity is not only present in normal stem cells but also in tumour stem cells as shown for CD133(+) glioblastoma-initiating cells." (PMID 26148697, 2015). "Therefore, our findings allow us to conclude that PKD2 may be a potential marker of HNSCC metastasis/tumor progression." (PMID 39408603, 2024).
tumor (continued). "Because PKD2 activity regulates the secretion of MMPs in other tumor cell lines, it could be speculated that pharmacological inhibition of PKD2/PKD3 activity in MDA-MB-231 cells blocks MMP secretion, thereby attenuating their autocrine signaling that maintains the cells in a post-EMT state." (PMID 37293129, 2023). "In addition, PKD2 stimulates the phosphorylation and proteasomal degradation of IkBα, thus triggering the NF-κB signaling pathway that culminates in the expression of angiogenic factors including VEGFα, thus promoting tumor angiogenesis and growth." (PMID 35805075, 2022). "Therefore, PKD2 is an interesting target kinase to inhibit tumor development and aggressiveness." (PMID 28890776, 2017). "Furthermore, it 3) raises the hypothesis of potential cooperation between various HSP90 client kinase proteins such as STK33 and PKD2, for a more robust and lasting effect during tumor development." (PMID 29100402, 2017). "PRDX2, PKD2 (polycystin-2), and AQP1 were overexpressed in tumor tissues, whereas SOD3 and KLF2 were downregulated." (PMID 41140697, 2025). "Both PKD2 and PKD3 have been proposed to promote tumor cell proliferation, migration/invasion, and angiogenesis." (PMID 39408603, 2024). "Do the protein expression levels of PKD2 and PKD3 in these tumor entities dictate which homodimer and/or heterodimer forms?" (PMID 37293129, 2023). "Currently, downstream BCR signaling molecules (PKD2 or BTK), tumor cell-derived IL-18 cytokine, and Breg-cell-mediated IL-35 are utilized to target pro-tumorigenic suppressor B cells in PDAC." (PMID 37033931, 2023). "For instance, in a TNBC cell line, HCC 1806, PKD2 and specially PKD3 were found to be key regulators of cell proliferation and tumor growth." (PMID 37293129, 2023). "Lnc-PKD2-2-3, miR-328, and GPAM expression in 30 pairs of CCA tumor and adjacent tissues, as well as in CCA cell lines, were determined." (PMID 35965521, 2022). "By validation using RT-qPCR in 30 CCA patients, it was observed that lnc-PKD2-2-3 and GPAM were elevated, whereas miR-328 was reduced in CCA tumor tissues compared with adjacent tissues (all P <0.01)." (PMID 35965521, 2022). "Overall, in contrast to the negative regulation of EMT, migration, and invasion by PKD1, PKD2 and PKD3 generally promote tumor metastasis by stimulating EMT and tumor cell migration/invasion in many cancer types." (PMID 33807058, 2021). "To date, several inhibitors of PKD2 have been developed, for example the small molecule inhibitor CRT0066101 and the pyrazolopyrimidine pan-PKD inhibitor SD-208, which both show anti-tumor activity in xenograft mouse models of various cancers." (PMID 32630675, 2020). "On phosphorylation mediated by PKD2, CIB1 contributes to angiogenesis by mediating PKD2-induced VEGF production and secretion of tumor cells and VEGFR2 expression." (PMID 31641356, 2019). "Most importantly, inhibition of PKD2 and PKD3 largely blocked tumor growth and angiogenesis in vivo." (PMID 30841931, 2019). "We were reminded of an earlier work showing that serine/threonine kinase PKD2 not only regulates HIF-1α, but also interacts with and participates to various functions coordinated by HSP90, including tumor growth and angiogenesis." (PMID 29100402, 2017). "The PKD family is composed of three members, namely PKD1(PKCμ), PKD2 and PKD3(PKCv), which can be activated by multiple stimuli, such as tumor-promoting phorbol esters, G protein-coupled receptor agonists and growth factors." (PMID 26683365, 2016). "PKD2 exhibits unique characteristics among the PKD family members, due to its pronounced role during physiological and tumour angiogenesis." (PMID 26148697, 2015).
tumor (continued). "Two genes (PKD1 and PKD2) coding for transient receptor potential polycystic (TRPP), a family of transient receptor potential (TRP) ion channels, were down-regulated in tumor tissues." (PMID 24466154, 2014). "The observed significant suppression of PKD2 and PKD3/PKCν by tirabrutinib are other potential phosphoregulations, which may be involved in the anti-tumor effects in TMD8." (PMID 36897912, 2023). "Subsequently, their expressions in CCA patients were detected in the present study, which observed that lnc-PKD2-2-3 and GPAM were elevated, while miR-328 was reduced in CCA tumor tissues compared to adjacent tissues, and they were closely inter-correlated with each other." (PMID 35965521, 2022). "To understand the role of B cell specific PKD2 function on tumor growth we reconstituted mice lacking mature B cells (μMT) with splenic B cells treated ex vivo with either CRT0066101 (PKDi) or DMSO followed by orthotopic injection of KPC cells." (PMID 35046933, 2021). "We observed no significant changes in tumor growth in the absence of host PKD2 function suggesting that cancer cell PKD function is the key driver of PDAC tumor growth." (PMID 35046933, 2021). "Accordingly, pharmacological inhibition of PKD or PKD2 knockdown in colon cancer cell lines blocked Akt and ERK signaling and suppressed NF-κB activity, leading to G2–M arrest and induction of apoptosis in vitro along with reduced tumor growth in vivo." (PMID 33807058, 2021). "Furthermore, PKD2 interacted with and was stabilized by the HSP90 chaperone protein in several human cancer cell lines to support tumor survival." (PMID 33807058, 2021). "Despite the presence of both conditions there was not additive effect of NF1 and PKD2 in terms of the severity of tumor development and/or ADPKD progression." (PMID 32533764, 2020). "Despite the presence of both conditions there was not additive effect of NF1 and PKD2 in terms of the severity of tumour development and/or ADPKD progression." (PMID 32533764, 2020). "In the present study, we found that PKD2 and PKD3 did not directly promote the tube formation of endothelial cells using co-culture with HUVEC cells directly, which imply that PKD2 and PKD3 may promote angiogenesis by remodeling tumor microenvironment." (PMID 30841931, 2019). "Significantly increased mRNA levels of PKD2 were detected in tumor tissues compared with non-tumor tissues." (PMID 26683365, 2016). "Since the role of both PKD2 and PKD3/PKCν in the pathology of DLBCL is unclear, further investigation is needed to clarify whether the observed regulations contribute to the anti-tumor efficacy of tirabrutinib in TMD8." (PMID 36897912, 2023). "Treatment with SD-208 significantly suppressed PKD2 activity in treated- vs. untreated-tumors, suggesting that SD-208 has reached the intended target and the inhibition of PKD may account for growth reduction of tumor xenografts." (PMID 25747583, 2015).
cancer (40 papers, 2012 to 2025). A tumor composed of atypical neoplastic, often pleomorphic cells that invade other tissues. "Their results demonstrate that HSP90 cleavage following NIPP treatment causes degradation of its client protein PKD2 and leads to impaired proliferation and increased cancer cell death in cancer cells." (PMID 37239142, 2023). "Cancer cells transduced with an expression vector encoding PKD2 (PKD2 o.e.)or empty vector (PKD2 e.v.) were subjected to pre-incubation with 50 nM PU-H71 for 24 hours before treatment with cold-plasma." (PMID 30858416, 2019). "Integrated phosphoproteome, transcriptome, and interactome showed that PKD2 was associated with multiple cancer‐related pathways, including adherent junction, regulation of actin cytoskeleton, and cell cycle‐related pathways." (PMID 30652415, 2019). "PKD2 was shown to be implicated in cancer cell growth, migration, invasion, and angiogenesis." (PMID 30858416, 2019). "To date, several studies have linked PKD3 levels to increased proliferation, cell motility, invasion and cancer stem cell maintenance and PKD2 to drug resistance, cell adhesion and migration." (PMID 38323010, 2024). "Consistently, PKD2 was necessary for autophagy induced by hyperosmotic stress in colon, cervical, and HeLa cancer cell lines." (PMID 37198573, 2023). "Therefore, it is possible that the recognition by 6B1 for HLA-A2–bound phosphopeptides derived from other cancer-associated proteins such as PKD2, which share similar amino acid compositions, might greatly expand the cancer target spectrum, allowing 1 mAb to target a wide array of cancers." (PMID 35260532, 2022). "These PKD2-mediated actions cause GOLPH3-induced activation of the PI3K/AKT/mTOR signaling pathway, thus promoting cancer cell proliferation." (PMID 35805075, 2022). "PKD2 promotes the proliferation of several cancer types, including glioblastoma, colorectal, pancreatic, breast, prostate and gastric cancers, through regulating multiple signaling pathways." (PMID 35805075, 2022). "Conversely, ectopic expression of PKD2 protected cancer cells from HSP90 inhibition-induced apoptotic effects in two in vivo mouse models." (PMID 33807058, 2021). "In fact, it has become increasingly clear that PKD2 and PKD3, opposite to PKD1, associate with more malignant cancer phenotypes and promote tumorigenesis and progression." (PMID 33807058, 2021). "PKD2 staining was observed in the cytoplasm of cancer cells, while E-cadherin staining was observed in a membranous pattern." (PMID 30718593, 2019). "Protein kinase D2 (PKD2) has been reported to be related with progression and invasion in various cancers." (PMID 30718593, 2019). "Integrated phosphoproteomes, transcriptomes, and interactome analysis reveals that PKD2 or PKD2&3 regulates multiple cancer‐related pathways." (PMID 30652415, 2019). "To this end, we investigated the oncogenic functions of PKD2 and PKD3 in vitro and in vivo, as well as their associated cancer‐related pathways through integrated omics study." (PMID 30652415, 2019). "There were discrepancies between Pkd1 mRNA levels and PC1 protein levels in some cancer cell lines, as well as discrepancies between Pkd2 mRNA levels and PC2 protein levels." (PMID 31251475, 2019). "To note, cleavage of HSP90/degradation of PKD2 is only one within several molecular events following delivery of cold-plasma to cancer cells." (PMID 30858416, 2019). "This is in line with the pro-migratory function of PKD2 in cancer and endothelial cells, and the fact that lysoPC induces monocyte migration in a PKD2-dependent manner." (PMID 29258556, 2017). "In cancer cells, PKD2 represents a core factor in the formation of a multiprotein complex that controls secretion of MMPs from the trans-Golgi network." (PMID 29258556, 2017). "An equally efficient strategy in cancers that underwent a switch from expression of PKD1 to the oncogenic versions PKD2/3 is the use of pan-PKD inhibitors like CRT0066101." (PMID 26848698, 2016).
cancer (continued). "Emerging evidence has demonstrated the involvement of PKD1 and PKD2 in several cancer hallmarks, including proliferation, apoptosis, and interaction with the tumor micro-environment, thus suggesting the potential contribution of this family of proteins to tumorigenic processes." (PMID 37510333, 2023). "Since ADPKD and cancer present several common molecular features, several authors proposed that mutations in PKD1 or PKD2 might be relevant in predisposing patients to kidney cancer." (PMID 37510333, 2023). "Most recently, some papers have been published on the correlation between PKD1 and PKD2 and cancer." (PMID 34064452, 2021). "Studies have been conducted to investigate the effect of PKD2 in various cancers." (PMID 30718593, 2019). "Furthermore, plasma-driven ROS triggered the cleavage of HSP90 chaperone and subsequent degradation of its client PKD2, previously shown to be essential for cancer cell proliferation and viability." (PMID 30858416, 2019). "Interestingly, treatment of cancer cells with cold plasma not only resulted in cleavage of HSP90, but was also associated with PKD2 degradation." (PMID 30858416, 2019). "Another study showed that NIPP-treated cancer cells (colon, prostate, breast) not only led to the cleavage of HSP90 but also related to the degradation of PKD2." (PMID 37239142, 2023). "Another study showed that sildenafil induced cell death of various cancer cells (MDA-MB-231, SW480, MIA PaCa-2, Panc1, BxPC3 and A549 cells) by changing the expression of HSP90 and degradation of PKD2." (PMID 35975844, 2023). "The PKD2 pro-proliferative function is mediated by inducing the PI3K/AKT/mTOR signaling pathway via GOLPH3, an oncogene that stimulates cancer cell growth by regulating this signaling cascade." (PMID 35805075, 2022). "PKD2 and PKD3 are overexpressed in some highly invasive cancer cells and are demonstrated to accelerate cancer cell invasion through the AKT, ERK and NF-κB signaling pathways." (PMID 26683365, 2016). "Because HSP90 bound and stabilized PKD2 in cancer cells, inhibition of HSP90 led to degradation of PKD2, thereby indirectly impacting the proangiogenic function of PKD2 under hypoxic conditions by blocking HIF1α accumulation and NF-κB/VEGF-A signaling activity." (PMID 33807058, 2021). "Looking for possible epigenetic associations between histone acetylation, microRNAs (miRNAs) and their targets in human cancer, the PC2 pathway is influenced by this epigenetic crosstalk; therefore, the epigenetic regulation of the PKD2 gene should be investigated and deciphered." (PMID 30597875, 2018). "In our work, PKD2 was significantly overexpressed regardless of cancer grade, which could be due to the miRNA activity." (PMID 36555458, 2022). "However, there were no studies investigating the correlation between PKD2 expression and prognosis in cancer patients directly." (PMID 30718593, 2019).
genetic disease (19 papers, 2007 to 2025). "Three patients with PKD2 gene mutation had another genetic disorder that overlapped ADPKD." (PMID 38790570, 2024). "ADPKD is a hereditary disease with complex phenotype and genetic heterogeneity, and most are caused by variants of the PKD1(16p13.3, 78%) or PKD2 (4p21, 15%) gene." (PMID 37953234, 2023). "Other than the genes identified as mutant in PKD (Pkd1 [the wild-type of which induces p21 ] and Pkd2), there is a striking paucity of gene targets in this common genetic disease." (PMID 17714589, 2007).
infection (6 papers, 2016 to 2024). The state of being infected such as from the introduction of a foreign agent such as serum, vaccine, antigenic substance or organism. "The infection and blocking efficiencies of different Pkd2 shRNAs were first verified in a kidney cell line and were further examined in primary cultured myocytes." (PMID 34901233, 2021). "PKD2 was overexpressed after transient transfection and remarkably knocked down after infection of lentivirus both at mRNA and protein level." (PMID 30718593, 2019). "Notably, PKD3 expression was observed to be in contrast to PKD1 and PKD2 from the early to late stages of infection, indicating the potential for different PKD family proteins to play distinct roles in the replication cycle." (PMID 39540754, 2024). "Moreover, infection of JurkaT-cells with PKD2-expressing shRNA revealed that the DRAK2 activation induced by anti-CD3 cross-linking or toxic carotenoids was greatly reduced by PKD2 knockdown." (PMID 36386181, 2022). "We found that both mRNA and protein levels of PKD1(Prkd1), PKD2 (Prkd2), and PKD3 (Prkd3) were increased after HCoV-229E or HCoV-OC43 infection." (PMID 39540754, 2024). "However, the expression of Pkd2, Pkhd1, Kif12, Cadherin16 and Socs3, which are known as HNF-1β target genes, did not change (data not shown), and only a few genes, including NR1H4, MITF, SLC3A1, and SLCO4C1, were significantly upregulated 9 h after Ad-HNF1B infection." (PMID 27196561, 2016).